ZFAS1 (ZNFX1 antisense RNA 1)
Diseases named in the same sentence as ZFAS1 in open-access papers (continued):
Sharing a sentence is not in itself a finding about the gene and the disease.
osteoarthritis (4 papers, 2019 to 2023). A noninflammatory degenerative joint disease occurring chiefly in older persons, characterized by degeneration of the articular cartilage, hypertrophy of bone at the margins and changes in the synovial membrane. "In this study, we aimed to reveal the protective roles of lncRNA ZFAS1 in osteoarthritis (OA) and further investigated its underlying mechanism." (PMID 37098630, 2023). "One study identified the critical role of lncRNA ZFAS1 in regulation of migration, apoptosis and proliferation of chondrocytes in osteoarthritis." (PMID 37779916, 2023). "LncRNA ZNFX1 antisense 1 (ZFAS1) reduced anti-oxidative stress via sponge of miR-1323 in osteoarthritis." (PMID 37779916, 2023). "ZFAS1 has also been shown to be dysregulated in the cartilage of osteoarthritis." (PMID 34268302, 2021). "In addition, ZFAS1 was found to promote chondrocytes proliferation, migration, and inhibit apoptosis and matrix synthesis in osteoarthritis (OA), and ZFAS1 expression level was downregulated in OA chondrocytes in comparison to mild chondrocytes." (PMID 31736958, 2019).
pancreatic adenocarcinoma (4 papers, 2020 to 2024). "The functions of ZFAS1 in pancreatic adenocarcinoma in vitro and in vivo were investigated by further bioinformatic analysis." (PMID 32550827, 2020). "Our results demonstrated the promotive effect of ZFAS1 on pancreatic adenocarcinoma metastasis and suggested its potential role as a novel regulator of ROCK2." (PMID 32550827, 2020). "ZFAS1 silencing inhibited pancreatic adenocarcinoma metastasis in vitro and in vivo." (PMID 32550827, 2020). "The long non-coding RNA ZFAS1 has been demonstrated to be an oncogene in some cancers, but its function and mechanism in pancreatic adenocarcinoma remain unclear." (PMID 32550827, 2020). "The ZFAS1 expression level in pancreatic adenocarcinoma was predicted by bioinformatic analysis, and the expression level of ZFAS1 in pancreatic adenocarcinoma tissue samples and cell lines was further detected by quantitative real-time PCR and in situ hybridization." (PMID 32550827, 2020). "ZFAS1 overexpression in pancreatic adenocarcinoma was predicted and experimentally verified." (PMID 32550827, 2020).
pulmonary fibrosis (4 papers, 2022 to 2024). Chronic progressive interstitial lung disorder characterized by the replacement of the lung tissue by connective tissue, leading to progressive dyspnea, respiratory failure, or right heart failure. "The lncRNA ZFAS1 was increased in the lungs of rats with pulmonary fibrosis induced by TGF-β1." (PMID 37367427, 2023). "ZFAS1 facilitates the transition of lung fibroblasts to myofibroblasts and ferroptosis by serving as a ceRNA via the miR-150-5p/SLC38A1 axis in the course of pulmonary fibrosis." (PMID 39296014, 2024). "lncRNA ZFAS1 acts as a competitive endogenous RNA (ceRNA) and sponge miR-150-5p to downregulate the expression of SLC38A1 to attenuate iron death and the progression of pulmonary fibrosis." (PMID 36187333, 2022).
Cirrhosis (3 papers, 2018 to 2026). A chronic disorder of the liver in which liver tissue becomes scarred and is partially replaced by regenerative nodules and fibrotic tissue resulting in loss of liver function. "A study found that levels of lncRNA ZFAS1 are higher in HCC patients than in healthy controls, and in patients with cirrhosis and hepatitis B, and the expression of ZFAS1 is correlated with serum AFP (alpha fetoprotein)." (PMID 31906046, 2019). "Expression of plasma ZFAS1 in hepatitis B and cirrhosis group was also higher than that in the healthy controls (P<0.001)." (PMID 29559565, 2018). "The levels of plasma ZFAS1 in HCC were significantly higher than those in healthy controls (P<0.001), and in patients with cirrhosis and hepatitis B (P<0.001), and was positively associated with serum α-fetoprotein (AFP)." (PMID 29559565, 2018). "Taken together, we clearly demonstrated that plasma levels of ZFAS1 are higher in HCC patients than that in healthy controls and in patients with cirrhosis and hepatitis B, and the expression of ZFAS1 is correlated to serum AFP." (PMID 29559565, 2018). "At last, ZFAS1 was chosen to be further analyzed in another 214 plasma samples including 79 control cases, 75 hepatitis B and cirrhosis patients, and 60 HCC patients." (PMID 29559565, 2018). "However, its limited cirrhosis-HCC differentiation capacity (AUC = 0.70 vs AFP's AUC = 1.00) underscores HCV-specific microenvironmental influences on ZFAS1 regulation." (PMID 41450817, 2026). "Plasma ZFAS1 in HCC is higher than that in control group (P<0.001) or in hepatitis B and cirrhosis groups (P<0.001)." (PMID 29559565, 2018). "To validate the expression of ZFAS1 is indeed up-regulated in HCC patients, we measured the levels of plasma ZFAS1 in 79 control cases, 75 hepatitis B and cirrhosis patients, and 60 HCC patients by RT-qPCR." (PMID 29559565, 2018). "We further explored the expression profiling of ZFAS1 in 79 control cases, 75 hepatitis B and cirrhosis patients, and 60 HCC patients, the expression of ZFAS1 is up-regulated from healthy, liver disease, and HCC step by step, which further validated our previous results." (PMID 29559565, 2018).
diabetic nephropathy (2 papers, 2022 to 2023). "The lncRNA ZFAS1 regulates the proliferation, oxidative stress, fibrosis, and inflammation of high glucose-induced diabetic nephropathy through the miR-588/ROCK1 axis." (PMID 35090549, 2022). "Altogether, our data suggest that ZFAS1 regulates the proliferation, oxidative stress, fibrosis, and inflammation of high glucose-induced diabetic nephropathy through the miR-588/ROCK1 axis." (PMID 35090549, 2022). "The ZFAS1 might be a novel biomarker for the early diagnosis, treatment, and prognosis of diabetic nephropathy in patients." (PMID 35090549, 2022).
diabetic retinopathy (2 papers, 2022 to 2024). "In diabetic retinopathy, ZFAS1 facilitates endothelial ferroptosis via miR-7-5p/ACSL4 axis." (PMID 39296014, 2024).
endometrial carcinoma (2 papers, 2021). A malignant tumor arising from the epithelium that lines the cavity of the uterine body. "Previous study has shown that upregulation of ZFAS1 in endometrial carcinoma predicted poor prognosis of the patients, and in vitro loss-of-functional assays validated the oncogenic role of ZFAS1 on endometrial carcinoma." (PMID 34703899, 2021). "The downstream miRNA–mRNA target involved in ZFAS1-mediated endometrial carcinoma progression was determined in this study." (PMID 34703899, 2021). "Knockdown of miR-34b counteracted with the suppressive effects of ZFAS1 silence on endometrial carcinoma cell proliferation, migration, and invasion." (PMID 34703899, 2021). "In line with the previous study, results in this study also showed that ZFAS1 was enhanced in endometrial carcinoma tissues and cells, and knockdown of ZFAS1 contributed to the suppression of endometrial carcinoma cell growth and metastasis." (PMID 34703899, 2021). "Second, functional assays demonstrated that siRNA-mediated silence of ZFAS1 suppressed endometrial carcinoma cell proliferation and metastasis." (PMID 34703899, 2021). "ZFAS1 functioned as a miR-34b sponge to promote the cell growth and metastasis of endometrial carcinoma through upregulation of VEGFA." (PMID 34703899, 2021). "In conclusion, lncRNA ZFAS1 functioned as an oncogene to promote endometrial carcinoma cell proliferation and metastasis through miR-34b/VEGFA axis." (PMID 34703899, 2021). "Third, ZFAS1 bind to miR-34b and negatively regulate expression of miR-34b in endometrial carcinoma cells." (PMID 34703899, 2021). "The increased cell apoptosis of HEC-1B induced by silence of ZFAS1 was restored by inhibition of miR-34b, revealing that silence of ZFAS1 suppressed endometrial carcinoma cell growth and metastasis through increase in miR-34b and decrease in VEGFA." (PMID 34703899, 2021). "Recent study showed that ZFAS1 promoted endometrial carcinoma cell proliferation and epithelial–mesenchymal transition." (PMID 34703899, 2021). "First, RT-qPCR analysis of endometrial carcinoma tissues and cells showed that ZFAS1 was enriched in endometrial carcinoma tissues and cells." (PMID 34703899, 2021). "Lastly, knockdown of miR-34b counteracted with the suppressive effects of ZFAS1 silence on endometrial carcinoma cell proliferation and metastasis." (PMID 34703899, 2021). "Our results also showed that ZFAS1 enhanced expression of VEGFA in endometrial carcinoma cells through decrease in miR-34b." (PMID 34703899, 2021). "This study first evaluated the expression level of ZFAS1 in endometrial carcinoma tissues and cells and then assessed the functional role of ZFAS1 on endometrial carcinoma cell growth and metastasis." (PMID 34703899, 2021). "Knockdown of miR-34b in this study contributed to endometrial carcinoma cell growth and metastasis, and attenuated ZFAS1 silence-induced suppression of endometrial carcinoma cell growth and metastasis." (PMID 34703899, 2021). "In summary, lncRNA ZFAS1 was found to be enhanced in endometrial carcinoma tissues and cells." (PMID 34703899, 2021). "Results in this study would give a new insight into the mechanism of progression of endometrial carcinoma and so as to suggest that lncRNA ZFAS1 might serve as a potential therapeutic target for the treatment of endometrial carcinoma." (PMID 34703899, 2021). "ZFAS1 was enhanced in the endometrial carcinoma tissues compared to adjacent tissues." (PMID 34703899, 2021). "Similarly, upregulation of ZFAS1 in endometrial carcinoma cell lines (HEC-1B, Ishikawa, KLE, and RL-952) was also verified by qRT-PCR." (PMID 34703899, 2021). "However, the in vivo regulatory role of ZFAS1 on endometrial carcinoma tumor growth should be investigated to provide more information about the suppressive effect of ZFAS1 on endometrial carcinoma." (PMID 34703899, 2021).
endometrial carcinoma (continued). "Since anti-VEGFA, bevacizumab, was widely used for the prevention of various cancers, silence of ZFAS1 might be a promising therapeutic strategy for the prevention of endometrial carcinoma through inhibition of VEGFA." (PMID 34703899, 2021). "pcDNA-mediated over-expression of ZFAS1 attenuated miR-43b mimic-induced decrease in mRNA and protein expression of VEGFA, indicating that ZFAS1 might sponge miR-34b to increase VEGFA in endometrial carcinoma." (PMID 34703899, 2021). "However, the underlying mechanism involved in ZFAS1-mediated endometrial carcinoma progression has not been fully understood." (PMID 34703899, 2021). "Therefore, we hypothesized that ZFAS1 might promote endometrial carcinoma progression through sponging of miR-34b." (PMID 34703899, 2021). "Moreover, miR-34b was verified as the sponging miRNA of ZFAS1 in endometrial carcinoma." (PMID 34703899, 2021). "Zinc finger nuclear transcription factor, X-box binding 1-type containing 1 antisense RNA 1 (ZFAS1) functions as an oncogenic long noncoding RNA (lncRNA) to promote proliferation and metastasis of endometrial carcinoma cell; however, the underlying mechanism has not been fully understood." (PMID 34703899, 2021). "Therefore, ZFAS1 might promote endometrial carcinoma progression through sponging of miR-34b." (PMID 34703899, 2021). "miR-34b was reduced in endometrial carcinoma and suggested negative correlation with ZFAS1 in endometrial carcinoma." (PMID 34703899, 2021). "The negative correlation between ZFAS1 and miR-34b in endometrial carcinoma tissues suggests that ZFAS1 might regulate endometrial carcinoma progression through sponging of miR-34b." (PMID 34703899, 2021).
epilepsy (2 papers, 2022 to 2025). A brain disorder characterized by episodes of abnormally increased neuronal discharge resulting in transient episodes of sensory or motor neurological dysfunction, or psychic dysfunction. "Transfection of pcDNA- ZFAS1 could promote apoptosis, while knockdown of ZFAS1 could inhibit the apoptosis and autophagy of hippocampal neurons by activating the PI3K/AKT pathway via up-regulating miR-421 in epilepsy." (PMID 36278003, 2022).
gastric cardia adenocarcinoma (2 papers, 2023). A carcinoma that arises from glandular epithelial cells of the cardia of stomach. "The high expression of lncRNA ZNFX1 antisense RNA 1 (ZFAS1) in gastric cardia adenocarcinoma (GCA) assists EPAS1 to enhance the epigenetic silencing of HIF-1α and promote the proliferation and metastasis of cancer cells." (PMID 36909247, 2023).
hepatoblastoma (2 papers, 2019 to 2024). Hepatoblastoma (HB) is a malignant hepatic tumor and is the most common pediatric liver cancer. "Similarly, research has identified that lncRNAs TUG1, HOXA-AS2, OIP5-AS1, ZFAS1, SNHG9, NBR2 and MIR205HG are significantly upregulated in HB cells and enhance cell proliferation, migration or invasion in hepatoblastoma." (PMID 38390281, 2024).
Hyperglycemia (2 papers, 2022 to 2023). An increased concentration of glucose in the blood. "Given that hyperglycemia is now regarded as the primary cause of DR by activating subsequent interconnecting biochemical pathways, the expression levels of ZFAS1 were detected in low and high glucose-cultured hRECs." (PMID 36092160, 2022). "Here, we provide the first evidence that in DR, hyperglycemia causes endothelial dysfunction via activating ferroptosis and ZFAS1/miR-7-5p/ACSL4 axis may serve as a key signaling in ferroptosis process." (PMID 36092160, 2022). "In our current study, we discovered that the expression level of lncRNA ZFAS1 was upregulated under hyperglycemia in both RNA sequencing dataset and in cultured hRECs." (PMID 36092160, 2022). "Altogether, we found that the lncRNA ZFAS1 was induced by hyperglycemia in hRECs and proposed that ZFAS1 may exerts its role by competitively binding with miR-7-5p and modulating the expression of its downstream mRNA ACSL4 expression." (PMID 36092160, 2022).
infarction (2 papers, 2019 to 2021). A localised pathological necrosis of tissue resulting from obstruction of the blood supply usually by a thrombus, an embolus, or vascular torsion. "Knockdown of ZFAS1 remarkably improved cardiac function via decreasing infarction ratio and increasing vWF expression, left ventricular ejection fraction, and left ventricular fractional shortening compared with group MI." (PMID 33952724, 2021).
ischemia (2 papers, 2019). A hypoperfusion of the BLOOD through an organ or tissue caused by a PATHOLOGIC CONSTRICTION or obstruction of its BLOOD VESSELS, or an absence of BLOOD CIRCULATION. "A knockdown of endogenous ZFAS1 attenuated ischemia-induced contractile dysfunction, whereas ZFAS1 overexpression impaired the contractility of cardiac muscles." (PMID 31694052, 2019). "Particularly, knockdown of ZFAS1 showed protective effects on the ischemia myocardium or hypoxia NMCMs This study strengthened the evidence that ZFAS1 might be a potential target for the treatment of MI." (PMID 31819041, 2019).
medullary thyroid carcinoma (2 papers, 2024 to 2025). "In medullary thyroid carcinoma, inhibition of ZFAS1 also inhibited tumor growth and metastasis through the miR-214-3p/UCHL1/EPAS1 pathway, providing evidence of its role in cancer aggressiveness." (PMID 41154428, 2025).
neuroblastoma (2 papers, 2016). Neuroblastoma (NB) is the most common solid, extracranial childhood tumor. "ZFAS1 was found extremely stable with a half-life of >32 hrs in neuroblastoma cells." (PMID 26928231, 2016).
cardiac hypertrophy (1 paper, 2020). "Indeed, ZFAS1 lncRNA inhibits SERCA2a activity in vitro and in live cardiomyocytes, and over-expression of ZFAS1 RNA in mouse left ventricle induces cardiac hypertrophy and ultimately heart failure." (PMID 33202832, 2020).
Cerebral ischemia (1 paper, 2022). Restriction of arterial blood supply to the brain associated with insufficient oxygenation to support the metabolic requirements of the tissue. "The lncRNA ZFAS1 protects neurons from injury and modulates inflammation, oxidative stress, apoptosis, cerebral ischemia-reperfusion injury by regulating miR-582-3p and NO levels." (PMID 36275741, 2022).
cervical tumor (1 paper, 2022). "Here, this study was carried out to investigate the roles and associations of ZFAS1, miR-190a-3p, and KLF6 in CC cell proliferation, and the enhancement of cervical tumor growth." (PMID 35112985, 2022).
cholangiocarcinoma (1 paper, 2019). A carcinoma that arises from the intrahepatic biliary tree (intrahepatic cholangiocarcinoma) or from the junction, or adjacent to the junction, of the right and left hepatic ducts (hilar cholangiocarcinoma). "In conclusion, the results presented that overexpressed ZFAS1 is associated with dismal prognosis for cholangiocarcinoma patients and this aberrant modulates proliferation and metastasis via miR‐296‐5p/USF1, which might activate oncogenes expression." (PMID 31565837, 2019). "In conclusion, ZFAS1 might promote cholangiocarcinoma proliferation and metastasis by modulating USF1 via miR‐296‐5p." (PMID 31565837, 2019). "In the present study, we investigated the pattern of lncRNA ZFAS1 in cholangiocarcinoma and evaluated the correlations between ZFAS1 expression, clinicopathological parameters and overall survival of CCA patients." (PMID 31565837, 2019).
chronic pancreatitis (1 paper, 2020). A chronic inflammatory process causing damage and fibrosis of the pancreatic parenchyma. "Pancreatic intraepithelial neoplasia (PanIN) and chronic pancreatitis samples should be collected to analyse the ZFAS1 expression level difference between cancer and precancerous lesions, so the diagnostic value of ZFAS1 in PAAD can be further validated." (PMID 32550827, 2020).
colorectal tumor (1 paper, 2019). "Besides the ones that were reported to be dysregulated in colorectal tumor samples, such as CCAT1, H19, DANCR, ZFAS1, SNHG16, CYTOR, we have identified many others in this study including LUCRC." (PMID 32082365, 2019).
coronary artery disease (1 paper, 2020). "Some studies have shown that lncRNAs could stably exist in peripheral blood mononuclear cells (PBMCs); for example, a lncRNA named OTTHUMT0000038702212 can serve as a unique biomarker to identify coronary artery disease (CAD), and ZFAS1 and CDR1AS13 also predict AMI with a higher specificity." (PMID 32332808, 2020).
encephalitis (1 paper, 2025). An acute inflammatory process affecting the brain parenchyma. "This suggests that ZFAS1 may act as a central regulatory hub in PRV-induced encephalitis." (PMID 41214723, 2025). "Notable lncRNA nodes, such as Zfas1, Gm20559, Neat1, C0300018K13Rik, and A230001M10Rik, were identified as central hubs, connecting to multiple target mRNAs, highlighting these transcripts as key lncRNAs in PRV-induced encephalitis." (PMID 41214723, 2025).
endothelial dysfunction (1 paper, 2022). In vascular diseases, endothelial dysfunction is a systemic pathological state of the endothelium (the inner lining of blood vessels) and can be broadly defined as an imbalance between vasodilating and vasoconstricting substances produced by (or acting on) the endothelium. "lncRNA ZFAS1 is a lncRNA on chromosome 20 and has been reported to play either oncogenic or tumor suppressor role in different cancers, while its role in endothelial dysfunction requires further study." (PMID 36092160, 2022). "Our data indicates that ZFAS1 is a major regulator of endothelial dysfunction and could be a new therapeutic target for the DR treatment." (PMID 36092160, 2022). "Taken together, these results imply that ZFAS1 may modulate ferroptosis-mediated endothelial dysfunction through ACSL4, a well-recognized promotor of ferroptosis, by sponging miR-7-5p." (PMID 36092160, 2022). "In conclusion, our results demonstrate that HG-induced ZFAS1 elevation activates ferroptosis in hRECs and the ZFAS1/miR-7-5p/ACSL4 axis may serve as a therapeutic target for endothelial dysfunction in DR." (PMID 36092160, 2022).